TNF (tumor necrosis factor)
Diseases named in the same sentence as TNF in open-access papers (continued):
Sharing a sentence is not in itself a finding about the gene and the disease.
Hypoalbuminemia (55 papers, 2013 to 2026). The concentration of albumin in the blood circulation is below the lower limit of normal. "A subgroup analysis of treatment failure revealed that hypoalbuminemia was associated with anti-TNF-α treatment failure, most likely due to intestinal biological drug loss." (PMID 36304532, 2022). "For example, hypoalbuminemia is associated with inflammation and synthesis of albumin is suppressed by pro-inflammatory cytokines TNF-α and Interleukin-1, both of which are important mediators of chronic inflammation in PWH." (PMID 36303554, 2022). "The inflammatory state and, particularly, high interleukin-6 and tumor necrosis factor (TNF)-alpha concentrations are the two main markers associated with hypoalbuminemia." (PMID 35010957, 2021). "The etiologies of hypoalbuminemia include malnourishment, hepatic impairment, decreased hepatic synthesis of albumin due to interleukin (IL)-1, IL-6, and tumor necrosis factor (TNF)-α, and protein loss via the kidney or gastrointestinal tract." (PMID 31731708, 2019). "Proinflammatory cytokines, such as interleukin-6 (IL-6) and tumor necrosis factor (TNF), are elevated and are associated with hypoalbuminemia, left ventricular diastolic dysfunction, and mortality in PD patients." (PMID 25286027, 2014). "Sustained release of inflammatory cytokines such as interleukin-6 or tumor necrosis factor-α may cause muscle and fat mass wasting and hypoalbuminemia in patients with metabolic disturbances." (PMID 38398372, 2024). "Furthermore, systemic inflammatory markers like C-reactive protein, interleukin-1, and the tumor necrosis factor are intricately linked with hypoalbuminemia due to their role in inhibiting albumin synthesis." (PMID 38473396, 2024). "With the activation of inflammatory cytokines, such as IL-6 or TNF-α, loss of appetite with subsequent muscle wasting and hypoalbuminemia may be seen." (PMID 35740095, 2022). "IL-1β and TNF-α may also contribute to the hypoalbuminaemia and weight loss seen in FIP via decreased albumin production and increased muscle breakdown respectively." (PMID 31835559, 2019). "TNF-α could selectively inhibit the gene expression of albumin, causing hypoalbuminemia." (PMID 36157419, 2022). "Hypoalbuminemia, commonly seen in cancer patients, results from cytokine-mediated catabolism (e.g., IL-6, TNF-α), reduced protein synthesis, and increased vascular permeability." (PMID 41156248, 2025). "Research has demonstrated that elevated levels of UA can stimulate the release of inflammatory cytokines such as interleukin-6 and tumor necrosis factor-alpha, which in turn inhibit albumin synthesis, leading to hypoalbuminemia." (PMID 39659906, 2024). "In cancer patients, tumor-related cytokines like tumor necrosis factor-α and interleukin-6 can hinder albumin gene transcription in liver cells, leading to hypoalbuminemia." (PMID 39767217, 2024). "Suppressed albumin synthesis is partly due to the activation of cytokines such as IL-1, IL-6, and TNF-α, a common observation in cancer, resulting in hypoalbuminemia." (PMID 37492594, 2023). "Hypoalbuminemia enhances the secretion of various inflammatory factors, such as interleukin-6 (IL-6) and tumor necrosis factor alpha (TNF-α), which further stimulates tumor inflammation progression." (PMID 37853186, 2023). "Albumin is widely recognized as an indicator of nutritional levels, and the mechanism of hypoalbuminemia is related to the increase in two inflammatory cytokines, tumor necrosis factor-α and interleukin-6, which inhibit the synthesis of albumin." (PMID 36386541, 2022). "The hypoalbuminemia seen in the 2% casein diet group can be attributed to significant increases in the levels of the acute-phase proteins TNF-α, IL-1, IL-6, and CRP compared with the controls." (PMID 32518615, 2020).
Hypoalbuminemia (continued). "Hotelling's t analysis revealed significant differences among the presurgical albumin infusion (B), presurgical normal protein diet (C), and hypoalbuminemia (D and E) diet groups in terms of serum levels of albumin, TNF-α, IL-1, IL-6, CRP, and MMP-8 (P=0.01)." (PMID 32518615, 2020). "Albumin is a negative acute phase protein; therefore, release of proinflammatory cytokines (eg, IL‐6, TNF) leads to reduced albumin synthesis in the liver and to hypoalbuminemia in cancer patients." (PMID 35847697, 2020). "The inflammatory state resulting from bacterial infection, which leads to the production of IL-1, TNF, and other cell mediators, can interfere with liver albumin synthesis, resulting in hypoalbuminemia." (PMID 31467670, 2019). "This adds focus to the higher peak and persistence of pro-inflammatory cytokines IL-6 and TNFα, hyperlactatemia, hypoalbuminemia, and corticosterone, as key mechanisms underlying non-survivorship after high-grade CLP." (PMID 41155249, 2025). "KD patients often exhibit varying degrees of hypoalbuminemia, which may be related to various inflammatory cytokines present, such as vascular endothelial growth factor, tumor necrosis factor-α, interleukin-1, and interleukin-6." (PMID 40574952, 2025). "Indeed, hypoalbuminemia correlates with increased levels of multiple inflammatory factors, such as interleukin-6 (IL-6) and tumor necrosis factor alpha (TNF-α), leading to tumor inflammation progression." (PMID 40216704, 2025). "Hypoalbuminemia also leads to hepatotoxicity among TB patients due to triggering inflammatory responses such as tumor necrosis factor (TNF) and interleukin (IL)-6 in TB patients, which leads to increased vascular permeability, increasing degradation, and decreasing synthesis of albumin." (PMID 39502524, 2024). "It is thought that SA also has a protective effect against endothelial damage and thrombotic state caused by free oxygen radicals, cytokines such as interlokin-6 and tumor necrosis factor alpha, and these protective mechanisms are insufficient in hypoalbuminemia." (PMID 37832116, 2023). "Hypoalbuminemia may also reflect the inflammatory activity induced by cytokines such as interleukin-6 (IL-6) or tumor necrosis factor." (PMID 31217896, 2019). "The result of hypoalbuminemia in patients with cancer might be due to cancer patient, pro-inflammatory cytokines (TNF-α, IL-2, and IL-6) induced positive acute phase reactant synthesis compete for nutrient in liver leads to decreases in serum albumin production." (PMID 36869395, 2023). "The results of our meta-analysis are in accordance with these reports, in which n-3 PUFAs reduced host inflammatory response by decreasing the concentration of IL-6, TNF-α, and CRP, and improving hypoalbuminemia." (PMID 28410575, 2017). "IMID exposure resulted in significant hepatocellular and neuronal damage characterized by elevated serum ALT and AST, hypoalbuminemia, hypoproteinemia, increased MDA, suppression of SOD and CAT activities, and upregulated mRNA expression of TNF-α, IL-6, and HMGB1." (PMID 41838129, 2026). "After abdominal infection, the absorption of endotoxin increases, thus stimulating the production of inflammatory mediators such as TNF, IL-1, and IL-6 in liver macrophages and inhibiting the translation of the ALB transcript, ultimately leading to hypoalbuminemia." (PMID 38166815, 2024). "IL-1, IL-6 and TNF-α, which are highly expressed in the serum of patients with hepatic alveolar echinococcosis, can inhibit the synthesis of ALB, which also leads to hypoalbuminemia; On the other hand, lymphocytes play an important role in immune monitoring and immune mediation." (PMID 34248983, 2021). "However, after pre- and postsurgical albumin infusion or administration of a normal protein diet, the levels of TNF-α, IL-1, IL-6, CRP, and MMP-8 were significantly reduced relative to the hypoalbuminemia group." (PMID 32518615, 2020).
Hypoalbuminemia (continued). "In patients with NRP, the lack of hypoalbuminemia could be due to the absence of certain cytokines, such as tumor necrosis factor and interleukin-1, which are typically released in those with primary nephrotic syndrome." (PMID 39768381, 2024). "In addition to the common inflammatory cytokines such as interleukin (IL)-6, IL-1β, IL-18, tumor necrosis factor (TNFα), IL-8, and C-reactive protein (CRP), hypoalbuminemia and elevated ferritin levels are also considered as inflammatory markers in patients with ESRD." (PMID 37038353, 2023). "Further studies have revealed plasma from acutely decompensated, but not compensated, cirrhotics had reduced TNF-α production in response to LPS stimulation by healthy monocytes, which was mediated by increased plasma prostaglandin E2 related to hypoalbuminaemia." (PMID 35195033, 2022). "Since the inflammatory cytokines TNF-α, IL-1, IL-6, and IL-8 play an essential role in the pathogenesis of AAV and negatively impact Alb levels, it could be suggested that hypoalbuminemia present in patients with AAV are proportional to the degree of inflammation." (PMID 35797397, 2022). "Previous studies have shown that hypoalbuminemia in CD patients could predict poor postoperative outcomes, whereas in those with acute severe UC it is correlated with treatment failure, higher colectomy rate, and non-response to anti-TNF therapy." (PMID 34834482, 2021).
Listeria infection (55 papers, 2005 to 2025). "Although case reports or a few case series of listeriosis have been reported to be associated with targeted therapy, most of the cases were related to anti-tumor necrosis factor-α monoclonal antibody." (PMID 35572995, 2022). "In a Listeria monocytogenes infection model, CSF-1/IL-34 blockade or treatment with anti-CSF-1 alone increased susceptibility to bacterial infection, although to a lower degree than anti-TNF therapy." (PMID 33162994, 2020). "We found that aCSF1/aIL34 blockade and aCSF1-treated mice were susceptible to Listeria infection; however, this susceptibility was better tolerated compared to standard of care TNF-FCRII neutralizing agent." (PMID 31552020, 2019). "For example, an increased risk for severe listeriosis is noted among individuals receiving immunosuppressive medications that interfere with cell-mediated immunity and production of TNF-α." (PMID 23653659, 2013). "In mice infected with L. monocytogenes, TNFα was produced early in infection and neutralization of TNFα exacerbated listeriosis." (PMID 34367171, 2021). "Here, we identify OTUB1 as an inhibitor of hepatocyte necroptosis in listeriosis and upon TNF stimulation." (PMID 33712742, 2021). "While IL-12, IL-6 and IFNγ are all inducible by TNF, IL-18 is a cytokine upstream of TNF that has been described as playing a role in protection from Listeria infection." (PMID 29438281, 2018). "Cytokines such as TNFα, IL-6, IL-8 play an important role in the control of listeriosis by neutrophil recruitment in mice." (PMID 28467447, 2017). "In this study, we detected significant induction and secretion of TNF-α in macrophages in response to Listeria infection." (PMID 29062315, 2017). "We observed that neonatal listeriosis patients also presented low TNF-α/IL-6 ratios, indicating predominant Th2 immune responses." (PMID 28903312, 2017). "Others have shown that during Listeria monocytogenes infection and other conditions in which GM-CSF is at high levels in circulation, Ly6Chigh monocytes differentiate into TNF/iNOS producing DCs (Tip-DC)." (PMID 28750033, 2017). "In Listeria monocytogenes infection, a specialized subpopulation of TNF and iNOS producing DCs (Tip-DCs) are the main producers of IFN-I in the spleen and are essential for early infection containment." (PMID 27459510, 2016). "We also observed that GAPDH1–22-activated MoDC from listeriosis patients with cancer released high levels of TNF-α while low levels of IL-6 and IL-10, suggesting a shifting toward Th1 pattern." (PMID 27965668, 2016). "Here, we report that GAPDH1–22 epitopes can activate MoDC of listeriosis patients with cancer receiving chemotherapy to release high levels TNF-α while low production of IL-6 and IL-10, a clear Th1 cytokine pattern." (PMID 27965668, 2016). "Innate immunity to Listeria in mice depends on tissue-resident macrophages and CD8α+ dendritic cells responding to Listeria infection by secreting pro-inflammatory cytokines including TNFα, IL-12, and IL-6." (PMID 25599590, 2015). "More than 15 reports on cases of Listeria monocytogenes infection after treatment with TNF-in have been made." (PMID 26558118, 2015). "During systemic listeriosis, Tip-DCs mediate protective effects due to their role as major producers of TNF and nitric oxide." (PMID 24586155, 2014). "The recruitment of inflammatory monocytes that produce TNF and NO for control of Listeria infection has been demonstrated to be crucial for anti-bacterial innate immune defense." (PMID 22629382, 2012). "IFN-γ and TNF-α are central to host immunity against listeriosis, but can compromise fetal survival." (PMID 15869716, 2005). "Considering the increased in vivo degradation of c-IAP1 in the absence of OTUB1, we studied whether OTUB1 protects hepatic c-IAP1 against proteasomal degradation in listeriosis and upon D-Gal/TNF treatment." (PMID 33712742, 2021).
Listeria infection (continued). "Immunosuppression secondary to TNF-α inhibitor therapy is a known risk factor for Listeria infection, 4, 5 although the American Academy of Pediatrics has not yet recommended empiric coverage in patients receiving TNF-α inhibitor therapy." (PMID 33217264, 2020). "Patients with neonatal listeriosis presented some biomarkers of poor prognosis, such as hypervirulent LM strains and low ratios of TNF-α/IL-6, as well as some biomarkers of better prognosis, such as high titres of anti-GAPDH1-22 antibodies and normal percentages of monocytes and CD8+ T cells." (PMID 28903312, 2017). "In addition, TNF-α protein expression was significantly attenuated in DUSP12 overexpressing cells compared to that in control cells upon Listeria infection." (PMID 29062315, 2017). "GRN-deficient mice failed to clear Listeria monocytogenes infection and allowed bacteria to proliferate, and also showed a substantial reduction in serum amounts of TNF-α and IL-6 upon administration of CpG-ODNs." (PMID 23755248, 2013). "Thus, OTUB1 prevented lethal listeriosis, liver necrosis, and production of TNF." (PMID 33712742, 2021). "In conclusion, antibiotic stress can trigger the biogenesis of MVs in L. monocytogenes and MVs produced by L. monocytogenes exposed to sub-MIC of AMP can induce strong pro-inflammatory responses by expressing TNF-α gene in host cells, which may contribute to the pathology of listeriosis." (PMID 33805671, 2021). "Cases of listeriosis were reported among patients undergoing therapy with other biologic agents such as infliximab (antitumor necrosis factor agents), etanercept (a tumor necrosis factor antagonist), and trastuzumab (a monoclonal antibody against the HER2 receptor)." (PMID 23175565, 2013). "Notably, Listeria monocytogenes infection at ZT8 (afternoon) resulted in reduced bacterial spread and stronger inflammatory responses than infections at ZT0 (morning), a difference associated with higher levels of IL-1β, tumor necrosis factor-alpha (TNF-α), interferon-gamma (IFN-γ), and CCL2." (PMID 40585526, 2025). "In IV Listeria infections, a subset of monocyte-derived DCs in spleens dubbed TIP-DCs contribute to bacterial control by producing TNF-α and inducible nitric oxide synthase–producing DCs." (PMID 33760886, 2021). "In comparison to wild type mice, Prak-deficient mice showed increased levels of inflammatory cytokines and chemokines, including IL-6, TNF-α, IL-12 p70, MIP-1β and MCP-1, in the serum upon Listeria infection." (PMID 33936034, 2021). "In this regard, all our patients developing neonatal listeriosis, had high titres of anti-GAPDH1-22 antibodies but low TNF-α/IL-6 ratios, confirming our efforts to formulate vaccines that increase Th1/Th2 ratios." (PMID 28903312, 2017). "We examined clinical cases of neonatal listeriosis in 2013–2015 and defined two useful prognostic immune biomarkers to design listeriosis vaccines: high anti-GAPDH1-22 titres and tumor necrosis factor (TNF)/interleukin (IL)-6 ratios." (PMID 28903312, 2017). "In Listeria monocytogenes infection, the absence of CCR2 leads to a lack of TNF/iNOS-producing (Tip) dendritic cells, resulting in severe TNF and iNOS deficiencies and impaired bacterial clearance." (PMID 39903705, 2025). "Next, we identified the cell population producing increased amounts of TNF in the absence of OTUB1 during listeriosis." (PMID 33712742, 2021). "In Listeria infection, previous work indicated that B10 cells inhibit CD4+ T cell expansion and bacterial clearance by macrophages through dampening the production of IFN-γ and TNF-α." (PMID 31474988, 2019). "Immunization with TNFKi did not alter immune cell migration into the liver during Listeria infection, whereas etanercept-treated and TNF−/− mice exhibited neutrophil accumulation and reduced macrophage recruitment in lesions." (PMID 29184553, 2017).
Listeria infection (continued). "Neonates born to non-vaccinated pregnant mice with listeriosis, showed brain and vascular diseases and significant microglial dysfunction by induction of TNF-α-mediated apoptosis." (PMID 28903312, 2017). "The repeated inhalation of such particles not only suppressed alveolar macrophages and T cell-mediated immune response to induced Listeria infection in rats, but also suppressed the in vitro production of IFN-γ, TNF-α, IL-1β and IL-6 by peripheral blood monocytes from healthy individuals." (PMID 26588473, 2015). "Moreover, studies indicate that antigen-specific expansion of Tcm cells in elderly results in heightened production of interferon gamma (IFNγ) and tumor necrosis factor (TNF) compared to their adult counterparts, leading to improved survival rates in Listeria monocytogenes infection." (PMID 40740500, 2025). "Therefore, these compounds could be considered for use as a potential treatment for listeriosis by inhibiting proteins such as, IL2, MAPK1, SRC, EGFR, PTPRC, TNF, IL1B, and ERBB2." (PMID 36671206, 2022). "Finally, based on the results observed following TNF-α treatment, it was of critical importance to test whether a similar ISG15-dependent modulation of cytokine secretion occurred during Listeria infection." (PMID 26259872, 2015). "We found that the production of proinflammatory cytokines, TNF-α, IL-6 and MCP-1, were impaired in the DUSP12 overexpressing cells, associated with reduced activations of p38 and JNK, but not ERK activation in response to LPS stimulation, BCG, and Listeria infection." (PMID 29062315, 2017). "Finally, control of secondary listeria infection does not require TNF-α." (PMID 28877252, 2017). "Production of Th1 cytokines MCP-1, TNF-α and IFN-γ and lack of production of Th2 cytokines such as IL-6 and IL-10, which are responsible for exaggerated inflammatory reactions and putative autoimmune responses in listeriosis, are features that are also relevant for protective DC vaccine vectors." (PMID 24600592, 2014).